TRIM65 (tripartite motif containing 65)
Diseases named in the same sentence as TRIM65 in open-access papers (continued):
Sharing a sentence is not in itself a finding about the gene and the disease.
esophageal squamous cell carcinoma (1 paper, 2025). Esophageal squamous cell carcinoma (ESCC) is a type of esophageal carcinoma (EC) that can affect any part of the esophagus, but is usually located in the upper or middle third. "Conversely, K48/K11-linked ubiquitin chains assembled by FBXW7 or TRIM65 target ANXA2 for 26S proteasomal degradation, leading to protein loss in FBXW7-deficient esophageal squamous cell carcinoma and conferring chemoresistance by upregulating MAPK signaling." (PMID 41185558, 2025).
gouty arthritis (1 paper, 2021). "Consistent with that, TRIM65 deficiency aggravated LPS-induced systemic inflammation and MSU-induced peritonitis and gouty arthritis in vivo." (PMID 34512673, 2021). "TRIM65-dificiency enhances disease severity in multiple mouse models of NLRP3-dependent acute inflammatory diseases: LPS-induced systemic inflammation and MSU-induced peritonitis and gouty arthritis." (PMID 34512673, 2021). "Collectively, these findings show that TRIM65 decreased disease severity in multiple mouse models of NLRP3-dependent acute inflammatory diseases (LPS-induced systemic inflammation and MSU-induced peritonitis and gouty arthritis) via suppression of the NLRP3 inflammasome." (PMID 34512673, 2021). "Moreover, we found that TRIM65 could alleviate LPS-induced systemic inflammation, MSU-induced peritoneal inflammation and gouty arthritis in vivo." (PMID 34512673, 2021).
Hepatic steatosis (1 paper, 2024). Steatosis is a term used to denote lipid accumulation within hepatocytes. "Severe hepatic steatosis in mice liver tissues were almost entirely reversed by Trim65 cKO in HCC in‐situ mice models, suggesting that Trim65 may participate in the regulation of lipid metabolism during pathogenesis." (PMID 39005234, 2024).
ischemia (1 paper, 2024). A hypoperfusion of the BLOOD through an organ or tissue caused by a PATHOLOGIC CONSTRICTION or obstruction of its BLOOD VESSELS, or an absence of BLOOD CIRCULATION. "We found that TRIM65 deficiency significantly increased PARP1 cleavage induced by intestinal ischemia-reperfusion injury." (PMID 38212319, 2024). "The results showed that TRIM65 was significantly decreased after 60 min of ischemia followed by 6 and 12 h of reperfusion compared to the sham operation group, particularly at 6 h, and then gradually increased during the remaining 24 h of reperfusion." (PMID 38212319, 2024).
lymph node metastasis (1 paper, 2024). "It’s interesting to note that the amount of TRIM65 was positively related to the lymph node metastasis of patients." (PMID 38777825, 2024).
lymphoma (1 paper, 2024). A malignant (clonal) proliferation of B- lymphocytes or T- lymphocytes which involves the lymph nodes, bone marrow and/or extranodal sites. "Interestingly, TRIM65 was shown to downregulate NLRP3 inflammasome activation, while in the setting of lymphoma, TRIM65 overexpression favors lymphoma cell survival via the ERK1/2 signaling pathway." (PMID 38397043, 2024). "Conversely, despite the suggested involvement in lymphoma development and the progression of TRIM11, TRIM13, TRIM19, TRIM32, TRIM35, TRIM65, data on their possible function regarding NLRP3 inflammasome regulation are lacking." (PMID 38397043, 2024).
renal clear cell carcinoma (1 paper, 2024). "Compared to adjacent normal tissues, TRIM65 was highly expressed in renal clear cell carcinoma samples." (PMID 38777825, 2024).
rhabdomyolysis (1 paper, 2025). Necrosis or disintegration of skeletal muscle often followed by myoglobinuria. "Western blot analysis indicated a notable elevation in TRIM65 expression in the kidneys of mice subjected to rhabdomyolysis and I/R‐induced AKI models." (PMID 40264575, 2025).
Salmonella Infections (1 paper, 2017). Infections with bacteria of the genus SALMONELLA. "Here we provide multiple lines of evidence, which strongly support the notion that SopA-mediated ubiquitination inhibits and triggers the proteasomal degradation of TRIM56 and TRIM65 during Salmonella infection." (PMID 28084320, 2017).
Sepsis (1 paper, 2021). Sepsis is defined as life-threatening organ dysfunction caused by a dysregulated host response to infection. "The effects of TRIM65 deficiency on LPS-induced sepsis were explored, and the outcomes showed that LPS increased IL-1β production in the sera of TRIM65-deficient mice." (PMID 34512673, 2021).
tumor (18 papers, 2019 to 2025). "In advanced HCC, elevated TRIM65 expression correlates with higher tumor grade, stage, and poorer prognosis." (PMID 40764998, 2025). "Functional experiments demonstrate that TRIM65 knockout diminishes tumor burden, suppresses M2 polarization, and enhances M1-like activation through the JAK1/STAT1 axis." (PMID 40764998, 2025). "Since the anchorage-independent growth of cancer cells is a key aspect of tumor phenotype which was related to the metastatic potential, we then explored the role of TRIM65 in the migration and invasion of RCC cells as well." (PMID 38777825, 2024). "Given the association between intratumor steatosis and the tumor immunosuppressive microenvironment in HCC, we then examined the alteration of the tumor immune microenvironment induced by TRIM65." (PMID 39005234, 2024). "The representative images showed that the expression of TRIM65 in ccRCC tumor tissues was much higher while the BTG3 protein levels were lower than the adjacent normal kidney tissues, which was further confirmed by the results of the IHC scores." (PMID 38777825, 2024). "To determine the effect of TRIM65 on RCC tumor growth in a more significant context, we then performed xenograft experiments using 769-P and ACHN cells in nude mice." (PMID 38777825, 2024). "In this study, we used cell counting/CCK8, colony formation, soft agar assay, and tumor xenografts to assess the effect of TRIM65 on the proliferation of RCC cells both in vitro and in vivo." (PMID 38777825, 2024). "In vivo experiments showed that inhibiting the expression of TRIM65 can also inhibit the growth of tumor cells, which is consistent with the in vitro experiments." (PMID 36035221, 2022). "In various tumors, TRIM65 can affect malignant biological tumor behavior by ubiquitination of related proteins." (PMID 36035221, 2022). "To further clarify the effect of TRIM65 on TNBC formation in vivo, we used a subcutaneous xenograft tumor model to study the effect of TRIM65 on TNBC." (PMID 36035221, 2022). "In the meantime, TF TRIM65 upregulates CUGBP Elav-like family member 2 (CELF2) to promote tumor apoptosis and inhibit cell migration and proliferation." (PMID 32211020, 2020). "Ectopic overexpression of TRIM65 enhanced the proliferation, invasion, and migration of tumor cells in vitro." (PMID 31332286, 2019). "Among the 50 CRC tissues with matched normal tissues, the mRNA level for TRIM65 was significantly higher in the tumor tissue." (PMID 31332286, 2019). "Tripartite motif-containing protein 65 (TRIM65) is an E3 ubiquitin ligase and a critical regulator of a variety of cellular processes as well as tumor progression." (PMID 31332286, 2019). "IHC staining revealed that TRIM65 and Ki67 were positively stained in the liver metastasis tumor clone (middle and low panels)." (PMID 31332286, 2019). "Moreover, as an oncogene, TRIM65 promoted cell growth and tumor metastasis in HCC via ubiquitylation of Axin1 to activate the β-catenin signaling pathway." (PMID 40438593, 2025). "In particular, livers from Trim65fl/fl mice representatively showed substantive multifocal disease with multiple tumor nodules, even intratumoral hemorrhage and bile‐filled vesicles in advanced stages, whereas livers from Trim65 cKO mice represented mild focal lesions." (PMID 39005234, 2024). "The results showed that knockdown of TRIM65 lowered tumor weight and volume in mice." (PMID 36035221, 2022). "Conversely, overexpression of TRIM65 in the cells remarkably enhanced the migration of the cells compared with the corresponding controls, suggesting that TRIM65 was able to promote the migration of tumor cells." (PMID 35402260, 2022).
tumor (continued). "Since we’ve proved that TRIM65 can directly bind to BTG3 and facilitate its degradation via K48-linked ubiquitination, then we designed and performed rescue assays to confirm the role of TRIM65-regulated BTG3 degradation on the proliferation of tumor cells as well as the cell cycle." (PMID 38777825, 2024). "However, considering the complexity of the tumor microenvironment, it remained to be determined whether TRIM65 contributes to the pathogenesis of HCC." (PMID 39005234, 2024). "We also tested whether TRIM65 expression in cancer cells affects tumor growth in vivo." (PMID 31332286, 2019). "In this study, we identified TRIM65 as a novel oncogene in RCC, which enhanced the tumor cell proliferation and anchorage-independent growth abilities both in vitro and in vivo." (PMID 38777825, 2024). "In summary, we demonstrated that TRIM65 serves as a central oncogene through the activation of YAP1 and up‐regulation of UDP‐GlcNAc and FFA levels, thus promoting the tumor immunosuppressive microenvironment in HCC." (PMID 39005234, 2024). "Consistently, Trim65 cKO mice showed remarkably prolonged survival and a suppression of HCC with less tumor nudes and abrogated malignant proliferation induced by DEN/CCl4." (PMID 39005234, 2024). "Therefore, TRIM65 may be an anti-tumor target affecting the polarization of TAMs." (PMID 38542388, 2024). "By examining the tumor size, growth curve, and tumor weight, we found that the volume and weight of TNBC tumors were significantly lower after 6 weeks in the sh-TRIM65 group than in the NC group." (PMID 36035221, 2022). "The tripartite motif-containing protein 65 (TRIM65) is an E3 ubiquitin ligase and a critical regulator of a variety of cellular processes as well as tumor progression." (PMID 35309939, 2022). "TRIM65, a number of the tripartite motif (TRIM) family, has E3 ubiquitin ligase activity and plays a crucial role in tumor progression and miRNA pathway, while the function in innate immunity is still unclear." (PMID 34512673, 2021). "Considering YAP1 functions as a sensor in the tumor microenvironment, we performed a metabolic analysis, which showed that uracil metabolism was significantly enriched with UMP, uracil, uridine, and UDP‐GlcNAc decreasing after TRIM65 knockdown." (PMID 39005234, 2024). "We observed that downregulation of TRIM65 can also significantly suppress the migration and invasion of tumor cells (data not shown), the mechanism and detailed phenotype will be further studied." (PMID 38777825, 2024). "Interestingly, NF2, a key tumor suppressor, responsible for activation of LATS1 (Large tumor suppressor homolog 1) and increased YAP1 phosphorylation, was significantly up‐regulated after silencing of TRIM65 expression." (PMID 39005234, 2024). "Moreover, TRIM65 overexpression can only regulate the anti-tumor effect of BTG3 rather than BTG3 K41R, indicating that TRIM65-regulated BTG3 ubiquitination and degradation are critical for its function in RCC." (PMID 38777825, 2024). "Similarly, YAP1‐5SA but not YAP1‐WT recovered the greatest tumor burden in Trim65 cKO mice, with a significantly elevated liver weight and liver‐body weight ratio." (PMID 39005234, 2024). "Furthermore, the expression of TRIM65 was positively correlated with M2 macrophage infiltration and negatively correlated with CD8+ T cell infiltration according to the analysis of the TIMER database, indicating that Trim65 contributed to the exhausted tumor immune microenvironment in HCC." (PMID 39005234, 2024). "Amino acid substitutions of the identified phosphorylation sites in TRIM65 (S–A, mimicking dephosphorylation status) did not abolish the migration ability of cancer cells, suggesting that the dephosphorylated form of TRIM65 protein might be more related to TRIM65 function in tumor progression." (PMID 31332286, 2019).
cancer (15 papers, 2019 to 2024). A tumor composed of atypical neoplastic, often pleomorphic cells that invade other tissues. "TEMRs are enriched in genic loci and can create potentially important risk alleles such as a deletion in TRIM65, a known cancer biomarker and therapeutic target." (PMID 36402840, 2022). "Despite the broadly described role of Annexin A2 as a poor-prognosis marker during cancer progression, it has recently been reported to be induced for degradation by other oncogenic E3 ubiquitin-ligases, such as TRIM65." (PMID 31952268, 2020). "As expected, downregulation of TRIM65 also repressed the colony formation of cancer cells." (PMID 38777825, 2024). "A deeper understanding of the ubiquitin proteasome system and the activity of TRIM65 E3 ligase may provide effective targets for novel cancer‐targeted HCC therapies." (PMID 39005234, 2024). "Similarly, supplement with BTG3 protein suppressed the colony formation of cancer cells elevated by TRIM65 overexpression." (PMID 38777825, 2024). "As an E3 ubiquitin ligase, TRIM65 is involved in ubiquitination in a large number of cancers." (PMID 36035221, 2022). "As a ubiquitin ligase, TRIM65 is reported to exert oncogenic functions in cancer biology." (PMID 34498706, 2021). "We next tested whether the TRIM65 expression level is related to cancer cell migration and invasion behavior." (PMID 31332286, 2019). "Thus, we tested the prometastatic functions of TRIM65 in vivo using the orthotopic implantation of cancer cells to construct a nude mouse metastatic model." (PMID 31332286, 2019). "It has been shown in previous studies that the E3 ubiquitin ligases, such as RNF146, TRIM11, TRIM32, TRIM54, TRIM65 and UBE3C promote various cancers by triggering Wnt/β-catenin signaling via degradation of Axin1." (PMID 37379772, 2023). "Clinical parameter analysis and in vitro cell-based assays indicated that TRIM65 promotes invasion and migration of CRC cells, thereby facilitating the metastasis of cancer cells in vivo." (PMID 31332286, 2019). "Thus, TRIM65 activates TGF-β/Smad signaling by alleviating its inhibition, thereby promoting cancer cell growth and progression." (PMID 39768197, 2024). "TRIM65 is a functional target of the microRNA miR-138-5p, which regulates autophagy and cisplatin resistance in the none small-cell cancer cell line A549/DDP." (PMID 33194618, 2020). "In sum, we identified a novel TRIM65–GAP–Rho regulatory axis that modulates the actin cytoskeleton and the migration ability of cells in CRC, which may represent a regulatory process for cancer cell migration and metastasis in general." (PMID 31332286, 2019).
infection (6 papers, 2015 to 2024). The state of being infected such as from the introduction of a foreign agent such as serum, vaccine, antigenic substance or organism. "We further demonstrate that SopA ubiquitinates TRIM56 and TRIM65, resulting in their proteasomal degradation during infection." (PMID 28084320, 2017). "Moreover, both proteomics and biochemical data revealed that TRIM56 and TRIM65 are degraded in the course of infection and heterologous SopA expression with protein levels being restored by proteasome inhibition." (PMID 28084320, 2017). "Infection of cycloheximide-treated cells induced robust SopA-driven degradation of TRIM56 and TRIM65." (PMID 28084320, 2017). "First, FLAG-tagged TRIM32 and TRIM65 (a control TRIM family member with established E3 ligase activity) were transfected into A549 cells followed by infection with PR8-Gaussia luciferase reporter virus." (PMID 26057645, 2015). "The tripartite motif-containing (TRIM) TRIM56 and TRIM65 host RING E3 ubiquitin ligases are normally involved recognizing foreign proteins and stimulating release of interferons to communicate to nearby cells to launch an immune response to combat infection." (PMID 33925937, 2021). "We observed significant enhancement of TRIM65 ubiquitination after infection with S. Typhimurium expressing wild type SopA but not after infection with a strain expressing the catalytic mutant SopAC753S." (PMID 27058235, 2016).
bacterial infection (1 paper, 2016). "The interactions between SopA and TRIM56 or TRIM65 were verified in transient co-transfection and bacterial infection experiments with epitope-tagged version of these proteins." (PMID 27058235, 2016). "This is consistent with the observation that SopA was able to ubiquitinate TRIM65 both in vitro and in vivo after bacterial infection or transient co-expression." (PMID 27058235, 2016). "We then investigated whether SopA could enhance the ubiquitination of TRIM65 during bacterial infection." (PMID 27058235, 2016).
TRIM65 also shares sentences with these, for which no sentence is quoted: adenocarcinoma (1 paper); depression (1); Leukoaraiosis (1); metastatic colorectal cancer (1); non-small cell lung carcinoma (1); ovarian carcinoma (1); peritonitis (1); pituitary tumor (1); proteopathy (1); squamous cell carcinoma (1).